DNMT1 (DNA methyltransferase 1)
Diseases named in the same sentence as DNMT1 in open-access papers (continued):
Sharing a sentence is not in itself a finding about the gene and the disease.
colon carcinoma (continued). "Loss of PPAR-α enhances colon carcinogenesis, indicated by increases in DNA methyltransferase 1 (DNMT1) and protein arginine methyltransferase 6 (PRMT6) in colon tumors from PPAR-α-deficient mice." (PMID 39494346, 2024). "To determine the potential clinical implication of DNMT1 gene deletion, we investigated DNMT1 gene deletion with protein consequence in human colon cancer." (PMID 37045940, 2023). "The data suggest that DNMT1 deletion alteration has specific gene expression profile consequences in human colon cancers." (PMID 37045940, 2023). "It is also reported that flavonoids and EGCG can inhibit DNMT1 enzyme activity to restore RXRα expression in human colon cancer cells; although they are less effective than drugs like Decitabine." (PMID 37107631, 2023). "In HCT116 colon cancer cells, disruption of DNMT1 and DNMT3B decreases the 5-mC concentration by 95% and delays cell proliferation." (PMID 37742010, 2023). "Previous studies have shown that inhibiting EZH2 or DNMT1 in colon cancer cell lines induces a neural-like differentiation phenotype." (PMID 37537688, 2023). "As shown in Fig. 8A1, gene knockdown of CDA resulted in marked inhibition of DNMT1 protein following decitabine treatment of colon cancer cells, and the results of 3 independent experiments are given as histograms (Fig. 8A1)." (PMID 37208732, 2023). "Mutations in DNMT1 and DNMT3a overexpression are features of both cancer patients and a mouse model of colon tumors; increased DNMT1 and DNMT3a expression contribute to hepatocellular carcinogenesis." (PMID 35054489, 2022). "Fenofibrate has also been proposed to suppress colon cancer cell proliferation in vitro and in in vivo xenograft models through epigenetic modifications involving the inhibition of DNA Methyltransferase 1 (DNMT1)." (PMID 35954274, 2022). "Targeted deletion of the DNA methyltransferase 1 (DNMT1) induced HACR2 expression in colon cancer cell lines, suggesting that DNMT1 is responsible for the silencing of HCAR2 in colon cancer." (PMID 36432618, 2022). "Reelin expression during colon cancer progression appears to be, at least “in part”, regulated by the DNMT-1-mediated methylation of its promotor region." (PMID 36290310, 2022). "Promoter DNA methylation of the SH3GL3 gene was previously inversely correlated with its expression in human colon cancer cell lines versus matched double knockout cell lines for DNMT1 and DNMT3b77." (PMID 36585414, 2022). "Colon cancer is a paradigm in which the roles of DNA methylation, DNMT1, and UHRF1 have been extensively investigated." (PMID 35625988, 2022). "Here, we found that HCT116 colon carcinoma cells inactivated for the DNA methylases DNMT1/3b undergo a partial epithelial to mesenchymal transition associated with increased CD44 variant exon skipping." (PMID 34086943, 2021). "It has been reported that knocking down of DNMT1 in colon cancer cells resulted in global demethylation of CpG sites, suggesting that DNMT1 is important for global methylation of CpG sites." (PMID 34268315, 2021). "In colon cancer, intestinal PPARα protects against colon carcinogenesis via regulation of methyltransferases DNMT1 and PRMT642." (PMID 33414412, 2021). "Colon cancers are sustained by global DNA hypomethylation, plausibly attained through the diminished activity of DNMT1 enzyme." (PMID 34947512, 2021). "High expression levels of DNMT1 protein have been found in human colon cancers, and this overexpression was correlated with HAUSP protein expression." (PMID 35052383, 2021). "Later on, 148 other lncRNAs were identified as interactors of DNMT1 in colon cancer cells by RIP-seq." (PMID 33142861, 2020). "For example, several studies have revealed the elevation of DNMT1 in human colon adenocarcinoma specimens and colon tumors from patients." (PMID 32918845, 2020).
colon carcinoma (continued). "It has been reported that TSA can activate certain hypermethylated genes, including CDKN2B, CDKN2A, MLH1 and TIMP3 in colon cancer cells after Dnmt1 inhibition by DNA demethylating agent such as 5-aza-dc." (PMID 32334468, 2020). "Similar to our findings, a previous study reported rDNA destabilization upon genetic ablation of DNMT1 and DNMT3b in human colon cancer cells." (PMID 33081395, 2020). "We discovered a novel epigenetic pathway that circFoxp1 recruits DNMT1 to hyper-methylate the promoter Foxp1 in colon cancer cells." (PMID 32951006, 2020). "Genetic modified human colon cancer cells that are DNMT1 hypomorph (DNMT1−/− cells) were compared to HCT116 wildtype (WT) cells." (PMID 31065074, 2019). "Although single knockout of either Dnmt1 or Dnmt3b gene had minimal effects on DNA demethylation in colon cancer cells, 19 knockouts of both Dnmt1 and Dnmt3b genes led to demethylation and re‐expression of tumor suppressor genes in these cells." (PMID 31090214, 2019). "In colon cancer, suppression of DNMT1 is sufficient to exhaust CSCs and inhibit tumor-initiating ability." (PMID 29721170, 2018). "IL-6 increases the expression of DNMT1 in colon cancer cells and enhances nuclear translocation of DNMT1." (PMID 28103274, 2017). "This study has demonstrated the relationship between hinokitiol and DNA methylation in colon cancer cells and provided evidence for the potential of hinokitiol as a novel DNMT1 inhibitor for colon cancer treatment." (PMID 28241740, 2017). "The expression patterns of DNMT1 in normal colon cells and colon cancer cells were analyzed by RT-PCR and qRT-PCR." (PMID 28241740, 2017). "A previous study has demonstrated that inhibition of MAPK/Erk pathway can up-regulate p16 expression through promoter demethylation via down-regulating DNMT1 expression in colon cancer cells." (PMID 27458157, 2016). "DNMT1 and DNMT3B double‐knockout HCT116 colon cancer cells showed that let‐7a‐3 methylation is cooperatively maintained by the DNA methyltransferases DNMT1 and DNMT3B just like other genomic regions." (PMID 27097729, 2016). "Early study indicated that the specific inhibitors or siRNA-mediated knockdown of SAPK/JNK decreased DNMT1 expression, thereby inhibiting growth in colon cancer cells." (PMID 27421653, 2016). "Previously, we reported that DNA Methyl-Transferase 1 (DNMT1) depletion caused cell cycle arrest in IMR90 cells and aneuploidy in HCT-116 colon cancer cells missing p14ARF function in association with global DNA hypomethylation." (PMID 26771138, 2016). "In the present study, we showed radiation-induced hypomethylation in colon cancer cells, and we identified several hypomethylated genes that also showed upregulated gene expression and downregulated DNMT1 levels in their promoter regions." (PMID 25887185, 2015). "Since it has been shown in the human colon cancer cell line HCT116 that downregulation of DNMT1 by siRNA induced a demethylation of the promoter of CDKN2A, we tested in HCT116 the same DNMT1 siRNA that we used in KG1." (PMID 25948775, 2015). "Most recently, studies have demonstrated that DNMT1 functions in the maintenance of human colon CSCs/CICs using the human colon cancer cell line HCT116 and its DNMT1 somatic knockout variant (DNMT1−/−)." (PMID 24822169, 2014). "Annurca apple polyphenol extracts inhibited the expression of DNMT1 and DNMT3b in colon cancer cells." (PMID 24822169, 2014). "More recently, it has been reported that Dnmt1 localizes to mitochondria in cultured mouse embryonic fibroblasts and human colon carcinoma cells and that Dnmt3a localizes to mouse brain and spinal cord mitochondria." (PMID 24399935, 2013). "The results are similar to those of reports that arsenic trioxide inhibits DNMT1 protein in human liver and colon cancer cells, we found that arsenic trioxide also inhibits DNMT3a protein in ER-negative breast cancer cells." (PMID 22558281, 2012).
colon carcinoma (continued). "A landmark study in the field has shown that reduced activity of DNMT1 suppresses intestinal tumorigenesis in a mouse colon cancer model]." (PMID 22563479, 2012). "Alternatively, DNA methyltransferase 1 (Dnmt1), which contributes to the maintenance of tumor suppressors silencing in colon cancer progression and in tumorigenic cell lines, is also upregulated by PyLT expression." (PMID 22355404, 2012). "DNMT1 was also reported to be overexpressed in human colon cancer (several hundredfold) in comparison to normal colon mucosa." (PMID 21629434, 2010). "It has been demonstrated that DNMT1 accounts for the majority of de novo methyltransferase activity in protein extracts from human colon cancer cells." (PMID 21629434, 2010). "Although decitabine treatment of colon cancer cells repressed DNMT1 protein expression by about 30% (Fig. 8A1), the additional gene knockdown of CDA enhanced decitabine’s ability to promote DNMT1 protein degradation, and depending on the cell line, its expression was reduced between 80 and 90%." (PMID 37208732, 2023). "DNMT1 gene deletion occurred in ~ 9% human colon cancers and other cancer types at varying degrees." (PMID 37045940, 2023). "Moreover, through the genomic analyses in human colon cancers and other malignancies, we found that DNMT1 gene deletion had reduced protein expression and exhibited specific gene expression profiles in colon cancers." (PMID 37045940, 2023). "A minimum threshold of DNMT1 activity is required for colon cancer cells to remain viable." (PMID 35625988, 2022). "Thus, reelin and DNMT-1 mRNA levels change in opposite directions throughout colon cancer progression in both humans and mice, and the shift in the expression of both genes occurs at the same stage." (PMID 36290310, 2022). "Thus, in myeloid leukemia samples, the frequency of DNMT1 and DNMT3A mutations was high, whereas, in glioblastoma, renal cell carcinoma, and colon carcinoma, the total mutation rate was less than 9%." (PMID 34572812, 2021). "In addition, we measured the DNMT1 enzyme content in colon cancer cells and found a significant reduction in enzyme concentration upon high-dose treatment of fenofibrate." (PMID 33959155, 2021). "Therefore, DNMT1 is likely important for the methylation of CpG sites of CHK in colon cancer cells we reported." (PMID 34268315, 2021). "Furthermore, the expression of DNMT1 and DNMT3b were all elevated in human colon cancer tissues as compared to the adjacent normal colon tissues." (PMID 34268315, 2021). "By analyzing human colon carcinoma (HCT116) cells which are hippomorphic for DNMT1, and HCT116 wildtype cells, Raman microspectroscopy, and imaging could discriminate between low and high-methylation levels in both cell types." (PMID 32695677, 2020). "In this study, we found that the expression of circFoxp1 and Foxp1 in colon cancer tissues was negatively correlated, and circFoxp1 hypermethylated the promoter of Foxp1 by recruiting DNMT1, thereby inhibiting the expression of Foxp1, and ultimately promoting the colon cancer progress." (PMID 32951006, 2020). "This pathway may be an effective molecular target for colon cancer treatment through the re-activation of Cip/Kip and inhibition of DNMT1 genes." (PMID 34466608, 2020). "Similarly, Robert and collaborators demonstrated that DNMT1 was required to maintain aberrant CpG methylation in colon cancer cells." (PMID 29700299, 2018). "Indeed, it has been previously shown that catalytically inactive DNMT1 represses more than 1000 genes in colon cancer cells." (PMID 29416775, 2018). "Interestingly, deletion of the DNMT1 gene in a colon cancer cell line (HCT116), while resulting in slower growth, diminished genomic methylation levels modestly ~20%." (PMID 24822169, 2014).
colon carcinoma (continued). "In addition, DNMT1 induces hypermethylation of tumor suppressor genes to epigenetically repress their activation in tumorigenesis processes in many cancers including colon cancer." (PMID 20625516, 2010). "Dnmt1, but not Dnmt3a, was found associated with mitochondria from cultured mouse embryonic fibroblasts and human colon carcinoma cells, but mitochondrial surface-associated Dnmt1 was not ruled out by protease digestion of outer membrane-bound proteins as done here." (PMID 24399935, 2013). "Treatment of colon cancer HCT-116 cells with hinokitiol resulted in a time- and dose-dependent decrease in DNMT1 mRNA and protein expression." (PMID 41226811, 2025). "For example, DNMT1 interacts with the lncRNA DACOR1 to regulate gene expression and DNA methylation in colon cancer." (PMID 41226543, 2025). "Most regulators showed amplification in copy numbers, especially in colon cancer (COAD) and esophageal cancer (ESCA), while the CNV deletions were frequently found on TET2, ALKBH1, and DNMT1." (PMID 37332118, 2023). "β-Thujaplicin reduced proliferation in MCF7 cells, suppressed cancer stemness in glioma U87MG, induced cell cycle arrest, apoptosis, and DNA methylation via DNMT1 and UHRF1 in colon cancer, and restricted liver cancer growth by apoptosis and cell cycle arrest." (PMID 36697960, 2022). "Treatment of human colon cancer RKO cells with SGI-1027 led to the re-expression of silenced TSG and the degradation of DNMT1." (PMID 37077808, 2022). "Other lncRNAs that interact with DNMT1 and affect methylation are DACOR1 in colon cancer and HOXD-AS1 in lung adenocarcinoma." (PMID 36012258, 2022). "Similar findings were observed when HAUSP was knocked out in colon cancer cells, supporting the concept that HAUSP deubiquitinates and protects DNMT1 from proteasomal degradation, thereby promoting DNMT1 stability." (PMID 35052383, 2021). "In a recent study it was reported that 5-aza-CdR and TSA can significantly downregulate DNMT1 and HDAC1 and upregulate p21, p27, and p57 genes expression in colon cancer SW480 cell line separately but their joint application was not investigated." (PMID 33680048, 2020). "SFN (25 μmol/L) also induced NRF2 promoter hypomethylation and expression in human colon cancer (Caco-2) cells; however, the decrease in NRF2 promoter methylation was attributed to a decrease in the protein expression and activity of DNMT1." (PMID 32878338, 2020). "Previously, we reported the effect of DNA demethylating agents and histone deacetylase inhibitors on histone deacetylase 1, DNA methyltransferase 1, and CIP/KIP family in colon cancer." (PMID 32592383, 2020). "Next, we used WT cells of the human colon cancer cell line HCT116 and their DNMT1-hypomorph progeny showing a lower global DNA methylation." (PMID 31065074, 2019). "They generated double knockout of DNMT1 and DNMT3B, which eliminated most of DNA methylation in HCT116, a colon cancer cell line." (PMID 31497535, 2019).
colon carcinoma (continued). "Quantitation of protein showed that the increases in DNMT1 and TET3 were significant in the inflamed smooth muscle from anal or colon cancer samples." (PMID 29700293, 2018). "Our data demonstrated that hinokitiol decreased DNMT1 and UHRF1 expression and increased the level of TET1 in colon cancer cell line HCT-116." (PMID 28241740, 2017). "RRx-001 inhibited the growth of colon cancer cells (HCT 116) and decreased levels of the DNA methyltransferases DNMT1 and DNMT3a in a time and dose-dependent manner." (PMID 28149332, 2017). "In HT-29 colon cancer cells, butyrate was found to protect against genotoxicity induced by the secondary bile DCA, and lower DNMT1 levels." (PMID 29259973, 2017). "Wang and colleagues found that anthocyanins demethylated tumor suppressor genes such as CDKN2A, SFRP2, SFRP5 and WIF1, through the inhibition of DNA methyl transferase 1 (DNMT1) and DNMT3B in colon cancer cells." (PMID 26840292, 2016). "Black Raspberry-derived anthocyanins were first shown to inhibit DNMT1 and DNMT3B in colon cancer cells." (PMID 24822169, 2014). "With this in mind we examined the staining pattern of DNMT1 and Ac-H3 in AOM-induced colon tumors, compared with AOM-untreated normal crypts as well as AOM-treated normal-appearing crypts." (PMID 23717604, 2013). "DNA methyltransferases DNMT and histone modifications play important roles in DNA methylation, with overexpression of DNMT1 and deacetylation of histone H3 or H4 reported in colon cancer." (PMID 23717604, 2013). "Based on our model, a dual specific DNMT1 and DNMT3B inhibitor would be the most efficient approach to reverse the hypermethylation phenotype in colon cancer cells." (PMID 22563479, 2012). "Knowing that CpG hypomethylation is involved in BORIS activation, we compared BORIS expression in the HCT116 colon cancer cell line to HCT116 cells treated with 5aza-dC, and to HCT116 bearing a double knockout (DKO) of DNMT3b and DNMT1." (PMID 21079786, 2010). "Moreover, in colon cancer cells, the epigenetic silencing of CDKN2A and MLH1 genes was also correlated with enhanced levels of DNMT1 and DNMT3B." (PMID 38504782, 2024). "Recently, black raspberry-derived anthocyanins, a subclass of flavonoids, have been demonstrated to suppress the enzymatic activities and protein levels of DNMT1 and DNMT3B in multiple colon cancer cell lines, including HCT116, Caco-2, and SW480 cells leading to demethylation." (PMID 37111085, 2023). "The loss of PPARα in the intestines has been proposed to increase DNMT1 (methyltransferase 1)-mediated p21 methylation and PRMT6 (protein arginine methyltransferase 6)-mediated p27 methylation, thereby promoting the development of colon cancer." (PMID 37305395, 2023). "We profiled with 850k arrays three replicates of the well-characterized HCT116 human colon cancer wild type (WT) cell line and of its double knock-out (DKO) derivative, in which DNA methylation is strongly reduced because of deletion of the DNMT1 and DNMT3B DNA methyltransferase genes." (PMID 36354000, 2022). "DNMT1 and ZNF304 could form the complex required for tumor suppressor gene transcriptional silencing to protect colon cancer cells." (PMID 35889255, 2022). "Meanwhile, knocking down of DNMT1 in colon cancer cells significantly increased the ability of 5-Aza-CdR to increase expression of CDKN2A, indicating that DNMT1 may work additively or synergistically with other members of DNMT in regulating DNA methylation." (PMID 34268315, 2021).